ZNF621 (zinc finger protein 621)
Description:
May be involved in transcriptional regulation.
Synonyms: FLJ45246
Tractability: PROTAC: ubiquitination databases record sites on it.
Gene: Protein-coding gene on chromosome 3 (40,524,878 to 40,574,685, forward strand). Ensembl gene ENSG00000172888.
Subcellular location: Nucleus
Subcellular location (Human Protein Atlas): Nuclear speckles
Pathways (Reactome):
Gene expression (Transcription): Generic Transcription Pathway
Gene Ontology:
Molecular function: protein binding; DNA-binding transcription factor activity, RNA polymerase II-specific; RNA polymerase II cis-regulatory region sequence-specific DNA binding
Biological process: regulation of transcription by RNA polymerase II; regulation of DNA-templated transcription
Cellular component: nuclear speck; nucleus
Genetic constraint (gnomAD): Loss-of-function variants: 5 observed, 12.4 expected, observed/expected ratio (o/e) 0.4, 90% interval 0.21 to 0.85. The synonymous counts are far from expectation, so gnomAD's model fits this gene poorly and the ratio says little. Missense variants: 473 observed, 552.4 expected, observed/expected ratio (o/e) 0.86, 90% interval 0.79 to 0.92. Synonymous variants: 156 observed, 200.82 expected, observed/expected ratio (o/e) 0.78, 90% interval 0.68 to 0.89.
Homologues: Orthologues: chimpanzee ZNF621 (99% identical), macaque ZNF621 (97% identical), dog ZNF621 (86% identical), pig ZNF621 (86% identical), rabbit ZNF621 (63% identical). Paralogues in human: ZFP14 (42% identical), ZNF30 (41% identical), ZNF573 (41% identical), ZNF461 (41% identical), ZFP82 (41% identical), ZNF546 (40% identical), ZNF7 (40% identical), ZFP28 (40% identical), ZNF300 (40% identical), ZNF879 (40% identical), ZFP30 (39% identical), ZNF540 (39% identical), and 164 more.
Diseases named in the same sentence as ZNF621 in open-access papers:
ZNF621 is named in the same sentence as 2 diseases in open-access papers, as found by Europe PMC text mining. Sharing a sentence is not in itself a finding about the gene and the disease. The quoted sentences say what the papers report.
breast carcinoma (1 paper, 2017). "In the current study, we used MCF-7 breast cancer cell line to determine the effect of EFA-CLA, as potential ligands for peroxisome proliferator-activated receptors (PPARs), on identified in silico PPAR-responsive genes: BCAR3, TCF20, WT1, ZNF621, and THRB (transcript TRβ2)." (PMID 28458685, 2017).
tumor (1 paper, 2023). "Because previous studies have reported that RNA binding motif protein 47 (RBM47), zinc finger protein 621 (ZNF621), and cytosolic arginine sensor for mTORC1 subunit 2 (CASTOR2) function as tumor suppressors, we selected these genes for further verification." (PMID 37981573, 2023).